CAV1 (caveolin 1)
Diseases named in the same sentence as CAV1 in open-access papers (continued):
Sharing a sentence is not in itself a finding about the gene and the disease.
tumor (continued). "Our data suggest that Y14 phosphorylated Cav1 is a driver of metabolic control of both tumor cell proliferation and tumor cell motility and invasion." (PMID 31803361, 2019). "miR-204 has been reported as a sensitizer that enhances the anti-tumor effect of chemotherapeutic drugs; thus, we focused on the relationship between miR-204 and CAV-1 in CR-A549 and CR-PC9 cells." (PMID 30981205, 2019). "After decreasing the expression of CAV1, the inhibitory role of LINC81507 in NSCLC progression is reversed, suggesting that upregulation of CAV1 by LINC81507 contributes to the tumor suppressor role of LINC81507 in NSCLC." (PMID 31296840, 2019). "Previous investigations have reported the impact of Cav-1 on the tumor microenvironment in some cancers, such as prostate, breast, and pancreas." (PMID 31297035, 2019). "Cav1 tumor suppressor activity is conditional on expression of galectin-3 and receptor N-glycosylation while pCav1 acts in concert with galectin-3 to promote FA turnover and tumor cell migration and invasion." (PMID 31803361, 2019). "Cav-1 is the principle quantitative marker for caveolae and is believed to have tumour-suppressing capabilities by improving caveolae formation and consequently, cell signaling." (PMID 31619022, 2019). "The role of Cav-1 in gynecological tumor is also paradoxical acting a promoting or inhibiting role in tumor progression." (PMID 31759347, 2019). "Caveolin-1 is a transmembrane protein with both tumor promoter and suppressor functions that remain poorly understood." (PMID 31803361, 2019). "Regardless of Cav-1 expression in the tumor or stromal cells, we found that Cav-1 also had paradoxical role in different types of gynecological tumors, both in vivo and in vitro and in the same tumor from the same organ." (PMID 31759347, 2019). "MiR-203 is suggested to repress tumor invasion and migration through Cav-1 in pancreatic cancer cells (Panc-1 cells)." (PMID 31759347, 2019). "Intratumoral fibronectin alignment was correlated with increased metastatic burden suggesting Cav1 positive stroma are permissive for tumor progression." (PMID 31845647, 2019). "In a comparison of Cav-1 expression between primary lung and secondary BM (53% vs. 84% in paired samples, 52% vs. 78% in whole samples), Cav-1 expression in tumor cells was higher in secondary BM than in primary lung lesions of SQC." (PMID 31297035, 2019). "Other studies have reported higher Cav-1 expression in pT1 than in pT2–pT4 tumor cells of ADC but lower Cav-1 expression in pT1–pT2 than in pT3–pT4 tumor cells of SQC." (PMID 31297035, 2019). "Our data demonstrated that tumor growth inhibition correlated with reduced Cav1 and GLUT3 expressions, while Bax was up regulated when compared to vehicle." (PMID 31534543, 2019). "The membrane protein CAV1 possesses tumor-suppressor properties within stromal cells, whereas downregulation of stromal CAV1 correlated with cancer progression, invasion and metastasis and thus, a worse clinical outcome." (PMID 31014370, 2019). "Among those genes, CAV1, a principal structural component of caveolar membrane domains, has been widely reported to promote tumor invasion and metastasis." (PMID 31487431, 2019). "Clinical features, including age, sex, histology, presence of BM, and Cav-1 expression in the tumor cells, of 211 primary NSCLC patients were analyzed." (PMID 31297035, 2019). "Mechanically, miR-124-3p has a key role in repressing tumor progression by targeting Cav-1 and Flotillin 1 (FLOT1)." (PMID 31759347, 2019). "Previously, it was mentioned that tumor cells induce oxidative stress which leads to the autophagic degradation of CAV-1." (PMID 31426364, 2019). "Cav-1 expression in the SQC group was further elevated in tumor cells of BM compared to the primary lung lesions." (PMID 31297035, 2019). "In contrast, CAV1 re-expression in advanced tumours has been shown to promote metastasis, although this effect seems to be rather a consequence of extra-mitochondrial CAV1 signalling." (PMID 30209302, 2019).
tumor (continued). "The simultaneous expression of E-cadherin and Cav-1 is essential to stabilize cell-cell adhesion and play a tumor suppressor role." (PMID 31759347, 2019). "Ezrin also contributes to the connection between actin and caveolin-1-enriched vacuoles of tumor cells, which form the driving structure of the cannibalistic process." (PMID 31850347, 2019). "Elevated Cav-1 levels are detected in tumor tissues and serum from PCa patient and correlate with disease progression." (PMID 31685812, 2019). "Extrapolation to the clinical setting suggests that elevated CAV1, often observed in advanced-stage cancers, can be successfully targeted with existing treatments to reduce the metastatic potential of tumor cells." (PMID 31362353, 2019). "Cell viability assays demonstrated that Cav1-HALO expression significantly improved the viability of cholesterol depleted tumor cells when compared to Cav1-depleted ATV-treated cells alone or empty vector-transfected ATV-treated cells." (PMID 31534543, 2019). "A previous study indicated that Cav-1 displayed a tumor-suppressor role, which requiring the presence of E-cadherin." (PMID 31759347, 2019). "Together, these studies suggest a pathway by which tumor cells produce ROS which signal to fibroblasts and lead to the degradation of CAV-1 and, therefore, increased exosomal uptake." (PMID 31426364, 2019). "Work on H-Ras-transformed cells demonstrated that CAV1 also acts as a tumour suppressor by increasing intracellular Ca2+ levels to trigger cell death." (PMID 30209302, 2019). "For example, a more reactive stromal phenotype following a decrease of CAV1 expression by lysosomal degradation in fibroblasts was observed when cancer cells induced oxidative stress in the tumour-microenvironment." (PMID 30871022, 2019). "The phenomenon that Cav-1 promotes cells apoptosis or down-regulates downstream signaling pathways following cells detachment is beneficial for the prevention of tumor formation." (PMID 31759347, 2019). "The reduced tumor sizes from ATV treatment corresponded to loss of Cav1 and GLUT3, induced pro-apoptotic Bax, and lowered tumor cholesterol content." (PMID 31534543, 2019). "They found that caveolin-1 (CAV1) was consistently down-regulated both at the protein (Western blot) and mRNA levels, with the same effect observed in both tumor and normal tissues." (PMID 34322541, 2019). "Studies demonstrate that when fibroblasts and tumor epithelial cells are co-cultured in the presence of oxidative stress, CAV-1 is degraded in fibroblasts which can be prevented by the treatment of antioxidant and autophagy inhibitors." (PMID 31426364, 2019). "In fact, CAV-1 has been shown to be upregulated by the hypoxia-inducible factor (HIF)-α that enhances the oncogenic potential of tumour cells by increasing the cell’s proliferative, migratory and invasive capacities." (PMID 30917536, 2019). "How does caveolin-1 lose its inhibitory function as a tumor suppressor and instead promote tumor growth?" (PMID 30424755, 2018). "The 12 h window was chosen since immunoblotting and immunofluorescence data demonstrated that CAV1 was significantly reduced in the tumor with a concomitant increase in HER2 at the cell membrane at this time point." (PMID 30510281, 2018). "In HER2-positive tumor samples containing low expression levels of CAV1, HER2 exhibits predominant membrane staining." (PMID 30510281, 2018). "Here the authors show that caveolin-1 (CAV1) regulates HER2 density at the cell membranes and that CAV1 gene knockdown or protein depletion via the cholesterol modulator lovastatin, increases trastuzumab binding and anti-tumor activity." (PMID 30510281, 2018).
tumor (continued). "A large number of studies have shown that caveolin-1 is expressed at a low level in most tumors and is present as a tumor suppressor gene." (PMID 30424755, 2018). "Nevertheless, poorly differentiated cell lines mimicked upregulated expression of genes (in tumours) such as CAV1, COL4A1, and novel candidates such as TSPAN5, TENM2, C15orf48, PLAU, AHNAK2, FAM129A, PLAU and platelet-specific phosphofructokinase (PFKP)." (PMID 30176945, 2018). "The expression of caveolin-1 is low in most tumors, indicating its role as a tumor suppressor, but the specific mechanism is still unclear." (PMID 30424755, 2018). "CAV1 has also been reported to have a dual role as either a tumor suppressor or tumor promoter, depending on the type of cancer." (PMID 30246033, 2018). "Downregulation of cav-1 led to decreased expression of TJ-associated proteins, proteolysis of TJs, and opening of the blood–tumor barrier (BTB), whereas cav-1 OE restored the expression of TJ-associated proteins." (PMID 30572925, 2018). "Higher tumor Cav-1 level and lower stromal Cav-1 level were significantly associated with longer PFS of nab-paclitaxel and gemcitabine." (PMID 30348118, 2018). "Inflammation is an important player in tumor progression, but the role of caveolin-1 in generating an inflammatory milieu remains poorly characterized." (PMID 30246033, 2018). "Not surprisingly, a higher cell surface localization of HER2 was found in human tumor tissues containing low levels of CAV1." (PMID 30510281, 2018). "Molecular profiling and unbiased analysis of extensive datasets revealed that CAV1 selectively promotes a pro-oncogenic program from TGFβ signalling, while attenuating subsets of TGFβ targets established as tumour suppressors." (PMID 29402961, 2018). "We show that CAV1 is up-regulated in tumour epithelium in a subset of PCa patients, and this up-regulation is strongly associated with a significant loss of E-cadherin, a hallmark of mesenchymal conversion." (PMID 29402961, 2018). "By contrast, it is regarded as a tumor promoter because caveolin-1 overexpression facilitates cancer cell migration, invasion and metastasis, and also induces multiple resistances to anticancer agents." (PMID 29301501, 2018). "This proposed CAV1-YAP regulation is therefore likely a significant driver of key events in tumor progression." (PMID 30404014, 2018). "The reason that tumor Cav-1 levels serve as a predictive biomarker is mainly the role of Cav-1 in the transport of nab-paclitaxel." (PMID 30348118, 2018). "CAV1 is the major component of endocytic caveolae plasma membrane invaginations and plays a critical role in normal tissue architecture and tumor progression." (PMID 30301909, 2018). "Caveolin-1 expression is upregulated in the terminal development stages of various tumors and in various stages of urinary tumors, and it increases with tumor malignancy." (PMID 30424755, 2018). "Patients with high tumor but low stromal Cav-1 staining reached a longest PFS, which suggests that an optimal intratumor drug distribution is more drugs in tumor cells and less in stromal cells." (PMID 30348118, 2018). "CAV1-KO mice have been used extensively as a model to investigate tumor-related mechanisms, such as tumor growth, pathologic angiogenesis, and tumor invasion." (PMID 30246033, 2018). "Patients with high tumor but low stromal Cav-1 staining (13/45) had the longest PFS, with a median PFS of 10.1 months (95% CI 2.4–19.1)." (PMID 30348118, 2018). "Subsequent study showed that loss of Cav-1 in mesenchymal stromal cells leads to increased aerobic glycolysis via activation of HIF-1 and NFkB favouring tumour growth." (PMID 29967776, 2018). "In early stages of the disease, CAV1 has been shown to function mainly as a tumor suppressor, whereas at later stages, CAV1 expression has been associated with progression and metastasis." (PMID 29850392, 2018).
tumor (continued). "Caveolin-1 (CAV1) is known for its role as both a tumor suppressor and an oncogene, harboring a highly context-dependent role within a myriad of malignancies and cell types." (PMID 30005686, 2018). "Ovarian cancer studies concerning Cav-1 have shown it to be downregulated inboth primary cells and immortalized cell lines, indicating its likely action asa tumor suppressor." (PMID 31069311, 2018). "In cancer development, caveolin-1 has been reported to behave as a tumor suppressor in the early stage." (PMID 29301501, 2018). "We observed fainter, less stromal-localized CAV1 staining in the hematological malignancies with lower CAV1 expression in tumor biopsies compared to normal splenic tissue." (PMID 30005686, 2018). "The analysis is complicated in NSCLC by tumour cell upregulated Cav-1 being reported to correlate with poorer survival and resistance to therapy." (PMID 29416729, 2018). "Stromal cells from the tumor microenvironment express low levels of caveolin 1 and high MCT4 allowing them to expel lactate into the tumor microenvironment." (PMID 30231564, 2018). "Here we now show that tumors from Cav1-silenced PC3 cells were characterized by increasing amounts of reactive tumor stroma and a reduced growth delay after IR and that these tumors displayed significantly higher levels of the survival protein Akt." (PMID 28112237, 2017). "Yet, CAV1 also functions as a tumor suppressor in early stages of cancer, where expression is suppressed by epigenetic mechanisms." (PMID 29340103, 2017). "The change of CAV1 expression between cancer cells and their normal counterparts and the effects of CAV1 expression in cancer cells on tumor aggressiveness largely differ in different cancer types." (PMID 29099748, 2017). "Expression of caveolin-1 (Cav-1) is frequently altered in many human cancers and both tumor suppression and promotion functions of Cav-1 have been suggested based on its expression status." (PMID 29141593, 2017). "Although Cav1 has been considered as a putative tumor-suppressor and cavtratin is proposed as a drug candidate for delaying tumor progression, the target of cavtratin and their functions in different types of vascular cells are not well understood." (PMID 29100301, 2017). "Tissue analysed with Cav1 antibody showed mild to moderate staining for the tumour stroma and only mild staining for the normal stroma." (PMID 28531107, 2017). "Consistent with our previous models, we transplanted the BM from WT or Cav1 KO mice in 12-week-old lethally irradiated PyMT recipient mice (8 weeks before the first tumor onset)." (PMID 29212030, 2017). "To evaluate the potential biological relevance of the regulation of CAV1, we assessed the effect on the directed migration of tumor cells." (PMID 28099944, 2017). "Tyrosine phosphorylation, serine phosphorylation, and dominant-negative point mutations in these domains serve to functionally inactivate the tumor suppressor function of Cav-1." (PMID 28546853, 2017). "We recently demonstrated that stromal Cav1 levels in the tumor microvasculature are important to the outcome of RT19." (PMID 28112237, 2017). "Both tumor suppression and promotion roles of Cav-1 have been proposed on the basis of its expression status detected in cancers." (PMID 29141593, 2017). "In a total of 91 cases with nodal metastasis, high expression of Cav-1 of tumor cell in metastatic lymph nodes was observed in 15 (16.5%) cases." (PMID 28828003, 2017). "For example, stromal Cav-1 facilitates tumor invasion through force-dependent organization of the microenvironment." (PMID 29221162, 2017). "Abnormally low and high Cav-1 expression was more frequently observed in early and advanced cancers, respectively, suggesting the oncogenic switch of its function in tumor progression." (PMID 29141593, 2017).
tumor (continued). "In line with the results presented above co-implantation of PC3(−) prostate epithelial cells with HS5 fibroblasts showed that Cav1-silenced HS(−) fibroblasts promoted tumor growth of PC3(−) cells stronger than Cav1-expressing HS5(+) fibroblasts." (PMID 28112237, 2017). "Tumor size was measured for 35 days after the injection of si‐control or si‐Cav‐1 on the 10th and 14th days." (PMID 28514055, 2017). "Presumably, the more severe decrease in stromal cav-1 would result in the greatest overall increase in tumor fibronectin expression." (PMID 28187162, 2017). "A pattern characterized by decreased expression or loss of CAV1, cavin 1, and CD36 in the tumor stroma of high-risk cancer patients has been emerging." (PMID 29099748, 2017). "Although Cav-1 functions as a tumor suppressor molecule in several solid cancers, its loss from stromal cells positive for α-smooth muscle actin (α-SMA) leads to robust proliferation, increased extracellular matrix production, and activated TGF-β signaling." (PMID 28279189, 2017). "The role of Cav-1 and Cav-2 in endothelial proliferation and differentiation during fibrosis requires further investigation, because both apparently interfere with tumor-induced angiogenesis in distinct ways." (PMID 29250058, 2017). "The opposite effects of Cav-1 on tumor cell growth were disrupted if ERK expression is depleted, supporting that the mitogenic conversion of Cav-1 effect is linked to its reciprocal regulation of the ERK feedback phosphorylation of RAF." (PMID 29141593, 2017). "Silencing of Cav1 expression in PC3 cells resulted in increased tumor growth and a reduced growth delay after IR when compared to tumors generated by Cav1-expressing PC3 cells." (PMID 28112237, 2017). "Glutamine and caveolin-1 are key players in this autophagy-mediated interplay, in which CAFs and tumour cells support each other through glutamine production/secretion and autophagy stimulation." (PMID 29225688, 2017). "Previous studies reported that Caveolin-1 (Cav1) has both tumor-promoting and tumor-suppressive functions." (PMID 29212030, 2017). "Within the group of patients with weak stromal CAV1 expression, the recurrence rate was much higher; 37 (79%) of the 47 patients developed tumour recurrence, giving weak stromal CAV1 expression a positive predictive value for recurrence of 79%." (PMID 28515480, 2017). "Particularly, Cav-1 seems to act as a tumor suppressor at early stages of cancer progression but as an oncoprotein in advanced-stage cancer." (PMID 28546853, 2017). "Of the 145 gastric specimens, Cav-1 was highly expressed in tumor cells of 18 (12.4%) cases, while low expression was observed in 127 (87.6%) cases." (PMID 28828003, 2017). "We can therefore argue that Cav1 KO macrophages represent supportive MAMs, which mediate the escape from tumor cell dormancy and increase tumor cell proliferation independently of the primary tumor and initial tumor cell extravasation." (PMID 29212030, 2017). "As predicted, the opposite effects of Cav-1 on both tumor cell growth and inhibitory RAF phosphorylation were abolished if ERK is depleted." (PMID 29141593, 2017). "While all 64 normal and 16 benign tumor tissues we examined showed easily detectable mRNA levels of α and β isoforms of Cav-1 and -2, a substantial fraction of cell lines and primary tumors displayed abnormally low or high expression of the transcripts." (PMID 29141593, 2017). "Cav-1 null mice exhibit increases in tumor incidence, tumor area, and tumor number compared with wild-type counterparts." (PMID 29141593, 2017). "On the other hand, galectin-glycoprotein lattices can sequester EGFRs, protecting them from interacting with caveolin-1 scaffolds, and hence promoting GF signaling and tumor growth." (PMID 29084770, 2017). "High MIM-B and caveolin-1 expression was correlated with tumor satellites (P = 0.005), numbers (P = 0.006), encapsulation (P = 0.027), vascular invasion (P = 0.001) and TNM stage (P = 0.002)." (PMID 29221140, 2017).